FAM199X (family with sequence similarity 199, X-linked)
Synonyms: CXorf39
Tractability: PROTAC: ubiquitination databases record sites on it.
Gene: Protein-coding gene on chromosome X (104,166,453 to 104,195,902, forward strand). Ensembl gene ENSG00000123575.
Subcellular location (Human Protein Atlas): Golgi apparatus; Cytosol; Nucleoplasm
Gene Ontology:
Molecular function: protein binding
Homologues: Orthologues: chimpanzee FAM199X (99% identical), rabbit FAM199X (99% identical), dog FAM199X (99% identical), pig FAM199X (99% identical), mouse Fam199x (98% identical), rat Fam199x (97% identical), tropical clawed frog fam199x (87% identical), macaque FAM199X (86% identical), zebrafish fam199x (81% identical), guinea pig FAM199X (65% identical).